TRG-AS1 (TRG antisense RNA 1)
Synonyms: TCRGV
Gene: Long non-coding RNA gene on chromosome 7 (38,330,978 to 38,378,804, forward strand). Ensembl gene ENSG00000281103.
Diseases named in the same sentence as TRG-AS1 in open-access papers:
TRG-AS1 is named in the same sentence as 9 diseases in open-access papers, as found by Europe PMC text mining. Sharing a sentence is not in itself a finding about the gene and the disease. The quoted sentences say what the papers report.
hepatocellular carcinoma (2 papers, 2020 to 2021). A malignant tumor that arises from hepatocytes. "Besides, TRG-AS1 is overexpressed in hepatocellular carcinoma (HCC) cells, where it enhances HCC cell proliferation, migration, EMT, and invasion by sponging miR4500 to regulate the expression of BACH1." (PMID 34136488, 2021). "T cell receptor gamma locus antisense RNA 1 (TRG-AS1) has been reported to involve in the progression of glioblastoma, however the role and its underlying molecular mechanism in hepatocellular carcinoma (HCC) remain unknown." (PMID 32774161, 2020).
gastric cancer (1 paper, 2025). A primary or metastatic malignant neoplasm involving the stomach. "qRT-PCR results demonstrated that gastric cancer tissue specimens had substantially lower relative expression of TRG-AS1 than adjacent tissues, and it was also significantly lower in the four cancer cells than in GES-1 cells." (PMID 40442738, 2025). "Through investigating the downstream miRNA of TRG-AS1, we discovered that in gastric cancer, TRG-AS1 may function as a ceRNA to regulate miR-873-5p and that overexpressing miR-873-5p could reverse the inhibitory effect of TRG-AS1 overexpression on cancer cells." (PMID 40442738, 2025).
glioblastoma (1 paper, 2020). The most malignant astrocytic tumor (WHO grade IV). "T cell receptor gamma locus antisense RNA 1 (TRG-AS1) has been determined to be oncogenic in glioblastoma." (PMID 32774161, 2020).
leukemia (1 paper, 2021). A malignant (clonal) hematologic disorder, involving hematopoietic stem cells and characterized by the presence of primitive or atypical myeloid or lymphoid cells in the bone marrow and the blood. "Among these leukemia cell-specific MAEs, RPSAP58 (rs78322935) and TRG-AS1 (rs4373430) only expressed one allele in leukemia cells." (PMID 34722498, 2021).
liver cancer (1 paper, 2025). An epithelial or non-epithelial malignant neoplasm that arises from the liver. "Similarly, TRG-AS1 is abnormally expressed in liver cancer tissues, and TRG-AS1 silencing can significantly inhibit the proliferation and growth of cancer cells, as well as metastasis." (PMID 40442738, 2025).
lung carcinoma (1 paper, 2025). "However, other research has shown that miR‐224‐5p is decreased in lung cancer cells and TRG‐AS1 promotes lung cancer cell growth by upregulating the oncogene Smad4 through the sequestration of miR‐224‐5p." (PMID 39840666, 2025).
lymph node metastasis (1 paper, 2021). "Overexpression of TRG-AS1 is associated with advanced TNM stage, lymph node metastasis, and shorter overall survival, which promotes cell proliferation, invasion, and migration of TSCC (tongue squamous cell carcinoma) by mediating the miR543/YAP1 axis." (PMID 34136488, 2021).
TRG-AS1 also shares sentences with these, for which no sentence is quoted: cancer (1 paper); tongue squamous cell carcinoma (1).